SLC6A9 (solute carrier family 6 member 9)
Description:
Sodium- and chloride-dependent glycine transporter. Essential for regulating glycine concentrations at inhibitory glycinergic synapses. [Isoform GlyT-1B]: Sodium- and chloride-dependent glycine transporter. [Isoform GlyT-1C]: Sodium- and chloride-dependent glycine transporter.
Synonyms: GlyT-1; GlyT1; GCENSG; IS6
Tractability: Small molecule: a drug acting on it is in phase 2 or 3 trials; a structure with a bound ligand is known; a high-quality ligand is known; it belongs to a druggable protein family. Antibody: its Gene Ontology location is reachable by antibodies, with high confidence; UniProt places it where antibodies can reach, with medium confidence; UniProt predicts a signal peptide or a membrane-spanning region. PROTAC: ubiquitination databases record sites on it; a small molecule that binds it is known.
Target class: SLC superfamily of solute carriers; SLC06 neurotransmitter transporter family; Electrochemical transporter; Transporter
Chemical probes: Alx-5407 (high quality), CHEMBL526648
Gene: Protein-coding gene on chromosome 1 (43,991,500 to 44,031,467, reverse strand). Ensembl gene ENSG00000196517.
Subcellular location: Cell membrane
Subcellular location (Human Protein Atlas): Golgi apparatus; Nucleoplasm
Pathways (Reactome):
Transport of small molecules: SLC-mediated transport of neurotransmitters
Gene Ontology:
Molecular function: amino acid:sodium symporter activity; glycine transmembrane transporter activity; glycine:sodium symporter activity; transmembrane transporter activity
Biological process: glycine import across plasma membrane; glycine transport; neurotransmitter transport; positive regulation of heme biosynthetic process; positive regulation of hemoglobin biosynthetic process; regulation of synaptic transmission, glycinergic; sodium ion transmembrane transport; transport across blood-brain barrier; neurotransmitter uptake
Cellular component: apical plasma membrane; basal plasma membrane; basolateral plasma membrane; lateral plasma membrane; plasma membrane; dense core granule; endosome; membrane; hippocampal mossy fiber to CA3 synapse; parallel fiber to Purkinje cell synapse; postsynaptic density; postsynaptic membrane; presynaptic membrane; synaptic vesicle membrane
Genetic constraint (gnomAD): Loss-of-function variants: 29 observed, 72.73 expected, observed/expected ratio (o/e) 0.4, 90% interval 0.3 to 0.54. The upper end of that interval is the gene's LOEUF score, 0.54, which puts it in group 2 of 6, group 1 being the genes least tolerant of losing a copy. Missense variants: 629 observed, 882.31 expected, observed/expected ratio (o/e) 0.71, 90% interval 0.67 to 0.76. Synonymous variants: 310 observed, 358.86 expected, observed/expected ratio (o/e) 0.86, 90% interval 0.79 to 0.95.
Gene-disease validity (ClinGen):
ClinGen rates the evidence that SLC6A9 causes each of these diseases.
atypical glycine encephalopathy (autosomal recessive): Definitive. Atypical glycine encephalopathy is a rare form of glycine encephalopathy (GE) presenting disease onset or clinical manifestations that differ from neonatal or infantile GE.
Homologues: Orthologues: chimpanzee SLC6A9 (98% identical), macaque SLC6A9 (97% identical), mouse Slc6a9 (96% identical), rabbit SLC6A9 (96% identical), guinea pig SLC6A9 (95% identical), rat Slc6a9 (95% identical), pig SLC6A9 (94% identical), dog SLC6A9 (89% identical), tropical clawed frog slc6a9 (81% identical), zebrafish slc6a9 (77% identical). Paralogues in human: SLC6A5 (46% identical), SLC6A7 (46% identical), SLC6A14 (42% identical), SLC6A8 (41% identical), SLC6A12 (40% identical), SLC6A13 (40% identical), SLC6A11 (39% identical), SLC6A2 (38% identical), SLC6A6 (38% identical), SLC6A4 (38% identical), SLC6A3 (37% identical), and 6 more.
Diseases named in the same sentence as SLC6A9 in open-access papers:
SLC6A9 is named in the same sentence as 20 diseases in open-access papers, as found by Europe PMC text mining. Sharing a sentence is not in itself a finding about the gene and the disease. The quoted sentences say what the papers report.
schizophrenia (6 papers, 2008 to 2025). A major psychotic disorder characterized by abnormalities in the perception or expression of reality. "We investigated the association of SLC1A4, SLC1A5, SLC6A5 and SLC6A9 genes with schizophrenia in the Japanese population by analysing total 21 common SNPs." (PMID 18638388, 2008). "By contrast, the gene encoding the glycine transporter (SLC6A9) is a significant driver at CTP-15, which is almost exclusively associated with schizophrenia risk." (PMID 36369282, 2022). "Specifically, these are creatine deficiency syndrome, mental retardation, musculoskeletal disorders for SLC6A8, and schizophrenia and hypertension for SLC6A9." (PMID 26191006, 2015). "We report here association studies of schizophrenia with SLC1A4, SLC1A5 encoding neutral amino acid transporters ASCT1, ASCT2, and SLC6A5, SLC6A9 encoding glycine transporters GLYT2, GLYT1, respectively." (PMID 18638388, 2008). "We conclude that at least one susceptibility locus for schizophrenia is located within or nearby SLC6A5, whereas SLC1A4 SLC1A5 and SLC6A9 are unlikely to be major susceptibility genes for schizophrenia in the Japanese population." (PMID 18638388, 2008). "Recently, negative associations of schizophrenia with polymorphisms in SLC6A9 and SLC6A5 were reported in the Chinese and the German population, respectively." (PMID 18638388, 2008). "We concluded that at least one susceptibility locus for schizophrenia may be located within or nearby SLC6A5, whereas SLC1A4, SLC1A5 and SLC6A9 are unlikely to be major susceptibility genes for schizophrenia in the Japanese population." (PMID 18638388, 2008). "There has been no linkage with schizophrenia reported to the chromosome regions where SLC1A5, SLC6A5 or SLC6A9 are located." (PMID 18638388, 2008).
glycine encephalopathy (3 papers, 2022 to 2024). Glycine encephalopathy (GE) is an inborn error of glycine metabolism characterized by accumulation of glycine in body fluids and tissues, including the brain, resulting in neurometabolic symptoms of variable severity. "Patients with glycine encephalopathy harboring homozygous SLC6A9 mutations were reported to have increased glycine concentrations in the CSF or plasma." (PMID 37962965, 2024). "Mutations in SLC6A9 have been linked to the development of essential hypertension and have become causal factors of glycine encephalopathy." (PMID 36233781, 2022). "Homozygous mutations in the GlyT1 (SLC6A9) gene have been shown to cause a disease phenotype very similar but not identical to glycine encephalopathy or nonketotic hyperglycinemia, a disease previously associated with defects in the glycine cleavage system." (PMID 35269698, 2022).
depression (2 papers, 2016 to 2022). "In the current work, we focus on examining the association of the SLC1A2 rs4354668, SLC6A9 rs2486001, and SLC6A5 rs2000959 polymorphisms with major depressive disorder and its clinical variables in the Polish population." (PMID 36233781, 2022). "Further studies with more SNPs and larger sample size are needed to establish the role of SLC1A2, SLC6A9, and SLC6A polymorphisms in the pathogenesis of depressive disorders." (PMID 36233781, 2022).
papillary thyroid carcinoma (1 paper, 2017). "In patients with thyroid cancer, a positive correlation between SLC6A9-5:2 and PARP-1 was identified, and low SLC6A9-5:2 expression was associated with a worse prognosis of papillary thyroid carcinoma." (PMID 28086241, 2017).
thyroid cancer (1 paper, 2017). "In the current study, we reported that a low level of SLC6A9 indicates 131I resistance of thyroid cancer cells." (PMID 28086241, 2017). "We demonstrated that SLC6A9-5:2 was remarkably downregulated in 131I-resistant thyroid cancer cell lines and 131I-insensitive patients and was positively correlated with Poly (ADP-ribose) polymerase 1 (PARP-1) expression and its activation." (PMID 28086241, 2017). "The present study identified a functional long non-coding RNA, SLC6A9-5:2, which was involved in the radioactive therapy resistance of thyroid cancer." (PMID 28086241, 2017). "We will try to establish an orthotropic model to further evaluate the effects of SLC6A9 on thyroid cancer in vivo." (PMID 28086241, 2017). "In conclusion, this study demonstrated that SLC6A9 is downregulated in 131I-resistant thyroid cancer accompanied by PARP-1 inhibition." (PMID 28086241, 2017). "Higher SLC6A9 expression significantly increased PARP-1 expression in thyroid cancer cells and was accompanied by effective 131I treatment." (PMID 28086241, 2017). "Hence, our data provide a new lncRNA-mediated regulatory mechanism implying that SLC6A9-5:2 can be used as a novel therapeutic target for 131I-resistant thyroid cancer." (PMID 28086241, 2017). "As a result, we found that only fragment 1 of SLC6A9 transfection could significantly transform 131I-resistant thyroid cancer cells into the sensitive phenotype." (PMID 28086241, 2017). "After downregulating SLC6A9 or blocking PARP-1 artificially, the sensitive thyroid cancer cells mostly displayed a tolerant phenotype under 131I exposure." (PMID 28086241, 2017). "Furthermore, SLC6A9-5:2 overexpression was positively correlated with PARP-1 mRNA and protein levels, which restored the sensitivity of resistant thyroid cancer cells." (PMID 28086241, 2017). "Furthermore, our analyses revealed high SLC6A9 and SLC6A9-1 expression promote PARP-1 function in thyroid cancer." (PMID 28086241, 2017). "Therefore, our results imply that SLC6A9 acts as a stabilizer for 131I sensitivity by maintaining PARP-1 expression and may serve as a novel therapeutic agent for thyroid cancer patients with 131I treatment failure." (PMID 28086241, 2017).
Urea (1 paper, 2022). "SLC38A2 was the only one glycine transporter detected in No Wash sample, whereas SLC6A9 and SLC36A1 were specifically found in Urea Wash sample." (PMID 35085786, 2022).
infection (2 papers, 2025). The state of being infected such as from the introduction of a foreign agent such as serum, vaccine, antigenic substance or organism. "Based on these distinct expression patterns, we propose that PTGDS acts as a positive regulator amplifying inflammatory responses, while WISP2 and SLC6A9 may participate in negative feedback mechanisms controlling excessive immune activation during ST infection and HS." (PMID 40563970, 2025).
cancer (1 paper, 2017). A tumor composed of atypical neoplastic, often pleomorphic cells that invade other tissues. "Among 21 randomly assigned patients with 131I-resistant cancer, it was discovered that SLC6A9 expression was much lower in cancer cell tissues than in adjacent normal tissues." (PMID 28086241, 2017). "Next, we transfected SLC6A9 encapsulated plasmid into cancer cells, and PARP-1 was found to be positively correlated with SLC6A9 expression." (PMID 28086241, 2017). "It was observed that ATP supplementation protected cancer cells from apoptosis in SLC6A9-transfected sensitive cancer cells." (PMID 28086241, 2017). "To reveal the underlying mechanism of SLC6A9 downregulation in resistant cancer cells, a continuous complementary region was identified in the PARP-1 promoter sequence when we inspected the genomic sequence of SLC6A9." (PMID 28086241, 2017). "We introduced SLC6A9 siRNA into cancer cells, and PARP-1 expression was significantly decreased." (PMID 28086241, 2017). "Additionally, SLC6A9 downregulation in resistant cancer cells interfered with PARP-1 activity to influence therapeutic efficacy." (PMID 28086241, 2017). "Additionally, we confirmed that the DNA repair intensity was less active after SLC6A9 interference compared with that in the RNAsi NC group and protected cancer cells from apoptosis with 131I treatment." (PMID 28086241, 2017). "As described, SLC6A9 was identified to promote PARP-1 expression and subsequently lead to cancer cell apoptosis under excessive DNA repair and 131I exposure." (PMID 28086241, 2017).
SLC6A9 also shares sentences with these, for which no sentence is quoted: Hypertension (3 papers); Tumor (3); alcohol dependence (1); cognitive decline (1); dementia (1); developmental delay (1); diabetes (1); essential hypertension (1); ischemia (1); neurological disease (1); nutritional deficiency (1); psychiatric disorder (1).